CRP (C-reactive protein)
Diseases named in the same sentence as CRP in open-access papers (continued):
Sharing a sentence is not in itself a finding about the gene and the disease.
COVID-19 (continued). "Except for IgG 1/IgG 4, LY #, and HGB, the severe COVID-19 group exhibited significantly elevated levels of IL-2, IL-6, IgG 2/IgG 1, IgG Sum/IgG 1, IgG 2/IgG Sum, CRP, PT, INR, DD, WBC, NE #, NLR, RDW, and PDW in comparison to the non-severe COVID-19 group (p<0.05)." (PMID 38106427, 2023). "In a study of 781 COVID-19 patients, obese persons had higher initial and MAX CRP levels than the non-obese; for each 1-standard deviation increased CRP level, patients were twice as likely to be admitted to the intensive care unit, have hypoxemic respiratory failure, or die." (PMID 38003780, 2023). "C-reactive protein, lymphocytes, and CLR have been investigated in the diagnosis and prognosis of COVID-19 patients but there is a lack of information on CLR in co-existence of COVID-19 and PTE." (PMID 37653759, 2023). "However, in severe COVID-19 patients the strongest positive correlations were found only between plasma levels of ACT and SAA, hs-CRP and AAT, and between CP and AAT, and negative correlations between HP and ACT as well as between HP and ALB." (PMID 36514048, 2022). "Risk factors related to progression were reported in nonsevere COVID-19 patients, such as lymphocyte count, neutrophil count, CD4+ and CD8+ T cell counts, CRP, D-dimer, interleukin-6, interleukin-8, lactate dehydrogenase, age, dyspnoea on admission, and hypertension." (PMID 35619076, 2022). "However, the findings of our study showed that interpretation of the biomarker levels is not quite easy and the role of CRP and PCT can be limited for the differential diagnosis of COVID-19 with other respiratory infections." (PMID 34493032, 2022). "In line with our findings, several investigations revealed that COVID-19 cases in the ICU had considerably higher numbers of white blood cells and neutrophils, in addition to elevated levels of CRP and other inflammatory markers when compared with the non-ICU cases." (PMID 36465717, 2022). "Instead, CRP had negative correlations with serum ATX levels or ⊿ATX, suggesting that inflammation might negatively influence serum ATX levels in COVID-19." (PMID 36369824, 2022). "C-Reactive Protein (CRP): We found CRP levels to be lower in the non-severe COVID-19 group compared to the non-COVID-19 group (coefficient = -−.15 p-value = 0.0001), whereas an opposite trend appears when compared to the severe COVID-19 group." (PMID 35842456, 2022). "Also, there is a statistically significant difference in D-dimer, CRP, Ferritin and LDH serum levels between non-severe and severe COVID-19 patients." (PMID 36522776, 2022). "Levels of coagulation parameters and inflammatory biomarkers groups (aPTT, fibrinogen, CRP, LDH, serum ferritin, and DD levels) were considerably greater in the COVID-19 death group than in the non-severe groups, although PC and AT-III levels were significantly lower." (PMID 35915103, 2022). "Lastly, the CRP levels were more elevated among pregnant women with SARS-CoV-2 infection who gave birth prematurely, compared with the control group of premature births without a history of COVID-19 (16.4% vs. 7.4%, p-value = 0.024)." (PMID 36579593, 2022). "Moreover, most acute phase proteins, such as SAA1, SAA2, SAA4, CRP, SERPINA3, and SAP/APCS, which were increased in severe COVID-19 patients were not changed in our CoronaVac immunized samples." (PMID 35686122, 2022). "In the prediction of a lethal outcome multivariate regression analysis in our research extracted only higher CRP values as an independent predictor in the non-COVID-19 group, while independent predictors in the COVID-19 group were older age (p ≤ 0.001), CCS (p = 0.019), and CRP (p = 0.015)." (PMID 36422354, 2022). "The level of CRP (mg/L) was significantly higher in the ARDS-COVID-19 group [40.3 (6.05–72.60)] when compared to the non-ARDS-COVID-19 [12.30 (5.00–48.00)] and suspected non-COVID-19 [4.330 (1.67–10.90)] groups." (PMID 33861750, 2021).
COVID-19 (continued). "IL-6, when combined with SARS-CoV-2 RNAaemia rather than with other markers such as SpO2/FiO2, CRP, and LDH, may be a pathological biomarker indicating deterioration of primary COVID-19 rather than secondary inflammation." (PMID 34379684, 2021). "Notably, CRP, PCT, and LDH levels were not as frequently elevated in mild COVID-19 cases as it would be expected." (PMID 34123972, 2021). "The ROC curve results indicated that lower LDH, TP, CRP and higher ALB could predicted patients with COVID-19 whose nucleic acid would turn negative within 14 days." (PMID 33663273, 2021). "CRB-65, CRP and PSP in the ED have an excellent accuracy to rule out early mortality in COVID-19." (PMID 34325711, 2021). "Despite a younger age, COVID-19 patients not expressing CHRFAM7A subunit showed features related to more severe disease, including higher level of C-reactive protein (p = 0.04) and more pronounced lymphopenia (p = 0.05 for total lymphocyte, p = 0.03 for % live lymphocytes)." (PMID 34088975, 2021). "Moreover, another study demonstrated that COVID-19 patients treated in the ICU had higher levels of LDH and CRP than those not treated in the ICU." (PMID 33713401, 2021). "Consistent with published predictive factors for COVID-19 outcomes, we found that the levels of LDH, ferritin, and CRP were significantly decreased in the non-survivals as compared with that in the survivals, and the number of lymphocytes was also markedly reduced in the non-survivals." (PMID 34987516, 2021). "It revealed that LDH, ALB, TP and CRP were correlated with whether nucleic acid turned negative within 14 days, AST, LDH, ALB, CRP and PCT were correlated with severity of COVID-19, and ALB and CRP was correlated with hospital stay > 31days or not (P < 0.05)." (PMID 33663273, 2021). "In our cohort, similar to previous studies, higher levels of IL-6, CRP, LDH, D-dimer, and troponin were found in non-survivors compared to survivors, further supporting the hypothesis of microvascular COVID-19 lung thrombo-inflammatory syndrome." (PMID 33355697, 2021). "In addition, unlike CRP and ferritin, IP-10 correlated well with mortality among ICU patients, likely reflecting its purported role as an effector of acute lung injury in COVID-19 disease progression." (PMID 33434221, 2021). "Moreover, TT, CRP, LDH, leukocytes, ferritin and IL-6 would be related not only with COVID-19 severity but also with mortality, in the same way as lymphocytes and TGF-β." (PMID 34439469, 2021). "Like the laboratory parameters of cancer patients with COVID-19, the median expression levels of CRP, mg/L (10.95, IQR [1.55–43.18]), and IL-6, pg/ml (12.30, IQR [5.48–28.22]) in COVID-19 patients without cancer were significantly higher than the upper limit of the normal reference range." (PMID 33192519, 2020). "Despite a negative COVID-19 nasal swab test, this patient’s suspicion for COVID-19 pneumonia remained high as his CXR had bilateral infiltrates along with laboratory findings of lymphopenia, elevated CRP, ferritin, and CPK levels, with plans for re-swab and serology testing." (PMID 40656321, 2025). "A similar pattern of expression was observed in our cohort, with elevated levels of SAA (p < 0.0001*), CRP (p < 0.0001*), and LBP (p < 0.0001*) alongside a decrease in ALB (p < 0.0001*) in all unhealthy individuals presenting ill at the hospital, regardless of COVID-19 status." (PMID 38879593, 2024). "There were significant d/span>differences in the laboratory findings between severe and non-severe COVID-19 cases in total WBCs (p value = .001), lymphocyte % (p value = .000), neutrophil % (p value=.038), RDW-SD (p value = .044), D-dimer (p value = .029) and CRP (p value = .044)." (PMID 37545971, 2023).
COVID-19 (continued). "In a study to detect the presence of secondary infection in COVID-19 patients using CRP and PCT, it was suggested that a rise or fall in CRP levels can predict the presence or absence of hospital-acquired infection in patients with COVID-19 and may necessitate antibiotic therapy." (PMID 39554800, 2023). "It should be noted that the laboratory tests such as ferritin, CRP, sedimentation rate, blood counts, liver function tests, and D-dimers used to estimate progression in COVID-19 patients, may already be elevated in patients with LSD regardless of COVID-19." (PMID 36794069, 2023). "In general, CRP and MDW showed increased values in infectious disease, and statistically significant differences were observed among the four groups of acute respiratory infections, nonrespiratory infections, the patients who had received treatment for COVID-19, and noninfectious disease (P < 0.01)." (PMID 36973757, 2023). "Thus, several biomarkers that have been associated with clinical myocarditis were found to occur in a majority of COVID-19 patients without a history of CVD that are under 50 years of age including troponin T, CRP, IL-6, CK-MB, D-dimer and kappa and lambda immunoglobulin FLCs." (PMID 36292038, 2022). "A recent meta-analysis that compared children with PIMS with COVID-19 patients pointed out that when compared to non-severe COVID-19 patients, PIMS patients presented lower absolute lymphocyte count along with more elevated absolute neutrophil count, D-dimers, and CRP levels." (PMID 36138657, 2022). "Indeed, cytokine blockade was not effective in COVID-19-unrelated ARDS (showing higher IL-6 levels but much lower CRP values as compared to severe COVID-19), while it is effective in CAR T-cell induced CRS (showing high concentrations of both IL-6 and CRP)." (PMID 35340805, 2022). "NLR is correlated with CRP and D-dimer level, therefore, NLR may serve as a reliable, cost-effective, and practical inflammatory biomarker for differentiating severe and nonsevere COVID-19 inpatients." (PMID 35741183, 2022). "However, IL-6 blockade may not be effective in some severe COVID-19, and largely depended on many factors including baseline IL-6 levels, PaO2/FIO2, requirement of HFO or NIV, levels of CRP, ferritin, D-dimer, and LDH." (PMID 35632823, 2022). "Moreover it suggests a possible relation between COVID-19 and the lipid profile with a negative correlation between CRP, LDL-C, and HDL-C values, proposing the hypothesis that lipid lowering could follow the rising of the COVID-19 inflammatory state." (PMID 34440605, 2021). "Additionally, the levels of inflammatory indices seem to be related to disease severity: COVID-19 patients admitted to intensive care unit (ICU) usually present higher levels of white blood cells, neutrophils, procalcitonin, and C-reactive protein (CRP) compared to non-ICU patients." (PMID 33478107, 2021). "Our finding, which confirmed that VAP/VAT and/or LCBI were significantly associated with a prespecified rise in PCT but not with a rise in CRP or WBC, suggests that serial PCT measurements could become useful in predicting the emergence of secondary bacterial infection in critical COVID-19 patients." (PMID 34827363, 2021). "Patients with COVID-19 have no specific laboratory findings but most of them have lymphopenia, elevated aminotransaminase levels, elevated LDH, elevated inflammatory markers [e.g., ferritin, C-reactive protein (CRP), and erythrocyte sedimentation rate], and abnormalities in coagulation tests." (PMID 33315350, 2020). "Similarly, one of the earliest reports identified higher CRP levels, higher brain natriuretic peptide levels, lower white blood cells, neutrophils and lymphocytes; and lower CD4 and CD8 counts in critically ill COVID-19 patients compared with noncritically ill." (PMID 33988463, 2021).
COVID-19 (continued). "Furthermore, patients with COVID-19 reported significantly lower white blood cell count (WBC) and lymphocyte count and higher CRP compared to controls, where WBC and lymphocytes, but not CRP, were significantly increased in patients with COVID-19 compared to non-COVID-19 patients." (PMID 34552795, 2021).
diabetes (3,734 papers, 2004 to 2026). "Our study revealed a significant association between the prevalence of DR and diabetes duration, HbA1c, CRP, and urinary albumin levels." (PMID 41541002, 2026). "More broadly, policies that already acknowledge biomarker “risk enhancers” in primary prevention (e.g., hs‐CRP and Lp(a)) offer a template for integrating diabetes‐relevant stroke biomarkers into shared decision‐making." (PMID 41567175, 2026). "Our study showed a strong association between the patients′ length of diabetes and higher HbA1c, CRP, and urine albumin levels, as well as the prevalence of DR." (PMID 41541002, 2026). "Widely available assays—hs‐CRP, Lp(a), albuminuria, and eGFR—can already guide preventive management and enhance risk prediction in diabetes." (PMID 41567175, 2026). "Overall, this review highlights inflammation as a measurable and potentially modifiable determinant of cardiovascular outcomes in diabetes, reinforcing the clinical value of hs-CRP beyond its observational association." (PMID 41835631, 2026). "The hazard ratio indicated that risk of diabetes was elevated (greater than 1) among those with vitamin D deficiency, regardless of CRP z-scores, but was highest among participants with lower CRP z-scores." (PMID 39662157, 2025). "This narrative review explores the interactions and overlapping pathways that converge within and modulate CRP, mCRP, the associated pathophysiology of diabetes mellitus, and cardiovascular disease." (PMID 40725102, 2025). "Elevated CRP levels have been consistently associated with increased cardiovascular risk in both the general population and in individuals with diabetes." (PMID 41010714, 2025). "Cardiovascular mortality was also associated with carotid VC score, diabetes, and CRP, but also with HD adequacy assessed by URR; covariates were significant factors in univariate analysis." (PMID 40136613, 2025). "Previous research primarily focused on conventional risk factors such as diabetes mellitus, smoking, and hyperlipidemia, with less emphasis on clinical biomarkers like C-reactive protein (CRP), platelet count, and uric acid (UA)." (PMID 41262309, 2025). "For example, adipocytes are cells with high metabolic activity that produce adipokines such as C-reactive protein, tumour necrosis factor alpha (TNFα) and interleukin-6 (IL-6), which increase the risk of diabetes and cardiovascular disease." (PMID 40142230, 2025). "The associations between vitamin D or CRP and incident diabetes remained statistically significant after adjusting for covariates (p < 0.001)." (PMID 39662157, 2025). "In univariate analysis, NT-proBNP, NT-proBNP/troponin ratio, CK-MB, myoglobin, age, C-reactive protein and non-insulin dependent diabetes mellitus (NIDDM) were associated with CLTI (all p < 0.05)." (PMID 40299905, 2025). "Chronically high levels ofhs-CRP also indicate the more common association between diabetes mellitus and some degree of chronic inflammation." (PMID 40978613, 2025). "Other significant risk factors for all-cause and cardiovascular mortality were diabetes, high CRP, and low albumin." (PMID 40136613, 2025). "We demonstrated that the co-existence of periodontitis and diabetes mellitus is significantly associated with elevated systemic inflammation, as measured by hs-CRP, and that this combined effect is more substantial than the presence of either condition alone." (PMID 41153725, 2025). "Although elevated CRP is consistently associated with cardiovascular risk, its predictive value in diabetes-related atherosclerosis should be interpreted in conjunction with other vascular aging markers and risk factors, rather than as a standalone biomarker." (PMID 40725102, 2025). "An elevated C-reactive protein to high-density lipoprotein cholesterol ratio is significantly associated with a higher risk of hyperuricemia in adults with diabetes or prediabetes, particularly in younger females." (PMID 40655403, 2025).
diabetes (continued). "C-reactive protein (CRP), as a blood marker of systemic inflammation, is commonly used as a risk indicator for cardiometabolic diseases, including coronary heart disease, diabetes, and hypertension." (PMID 40437222, 2025). "For instance, 1 study developed a model integrating 6 key predictors—age, diabetes, atrial fibrillation, antiplatelet therapy, C-reactive protein levels, and baseline NIHSS scores —to improve END risk stratification." (PMID 41370784, 2025). "Prospective studies have indicated that elevated CRP levels increase diabetes risk by 2- to 3-fold, with higher predictive sensitivity observed for hsCRP." (PMID 41357322, 2025). "Compared with traditional lipid and inflammatory markers, a higher CRP/HDL-c ratio was more strongly associated with an increased risk of HUA in patients with diabetes or prediabetes." (PMID 40655403, 2025). "In linear regression analysis, including both BMI and diabetes status as confounding variables, the positive association between CRP and IL-6 levels remained significant (p = 2.3e−4 and p = 0.03, respectively)." (PMID 40045464, 2025). "Higher CRP levels are associated with increased risks of various comorbidities in RA patients, including cardiovascular diseases, diabetes, metabolic syndrome, pulmonary diseases, and depression." (PMID 40002926, 2025). "All-cause mortality was associated with carotid VC score, diabetes, and CRP; covariates were all significant factors in univariate analysis and factors relevant to patients’ outcomes." (PMID 40136613, 2025). "The unfavorable association between vitamin D and C-reactive protein levels has been established in atherosclerotic vascular disease and diabetes mellitus, implying a similar relationship in endometriosis." (PMID 40565701, 2025). "There was a significant interaction between vitamin D deficiency and CRP on incident diabetes (p < 0.001)." (PMID 39662157, 2025). "This elevation in CRP following vaccination agrees with observations made in other research, especially among subjects with predispositions such as diabetes." (PMID 40406137, 2025). "Meanwhile, age, diabetes duration, and CRP showed a weaker association with DPN status (OR = 1.024, 95% CI: 1.003–1.046; OR = 1.008, 95% CI: 1.006–1.011; OR = 1.017, 95% CI: 1.003–1.031; P < 0.05 for all)." (PMID 41466234, 2025). "IFI30 genetic variants are associated with plasma C-reactive protein levels, hyperglycemia, and diabetes." (PMID 41356597, 2025). "The findings of this study showed that high preoperative CRP levels and a history of diabetes were associated with PJI following RSA." (PMID 40363957, 2025). "Deborah J Wexler and colleagues’ research explored the risk factors for diabetes, with elevated C-reactive protein levels increasing the risk of diabetes onset." (PMID 40950999, 2025). "We first linked vitamin D and C-reactive protein (CRP; inflammation measure) levels with incident diabetes during a mean follow-up of 13.5 years (SD = 1.9)." (PMID 39662157, 2025). "Carotid VC score over 4 was an independent predictor of all-cause and cardiovascular mortality, along with diabetes, low albumin, and high CRP." (PMID 40136613, 2025). "In terms of diabetes and hypertension, 55 and 6 CRP associated CpG sites were selected by lasso penalized regression." (PMID 40437222, 2025). "In conclusion, diabetes and high levels of hs‐CRP were risk factors for ISR in patients with AMI after PCI." (PMID 40056066, 2025). "This table summarizes major cohort and clinical studies investigating CRP and high-sensitivity CRP (hs-CRP) as predictive markers for incident diabetes, cardiovascular risk, and vascular complications." (PMID 40725102, 2025). "We validated the stronger associations of MRS-CRP with long-term sleep and metabolic conditions, such as OSA and diabetes, compared to blood CRP, which showed modest associations." (PMID 40437222, 2025).